GAGE12J (G antigen 12J)
Synonyms: OTTHUMG00000024137; GAGE11
Tractability: Antibody: the Human Protein Atlas places it where antibodies can reach.
Gene: Protein-coding gene on chromosome X (49,322,037 to 49,329,384, forward strand). Ensembl gene ENSG00000224659.
Subcellular location (Human Protein Atlas): Plasma membrane; Cytosol; Golgi apparatus
Gene Ontology:
Molecular function: protein binding
Homologues: Orthologues: chimpanzee GAGE10 (83% identical). Paralogues in human: GAGE1 (98% identical), GAGE12F (98% identical), GAGE12G (98% identical), GAGE13 (98% identical), GAGE12C (97% identical), GAGE12D (97% identical), GAGE12E (97% identical), GAGE12H (97% identical), GAGE2A (95% identical), GAGE2E (92% identical), GAGE10 (91% identical), PAGE1 (53% identical), and 10 more.
Diseases named in the same sentence as GAGE12J in open-access papers:
GAGE12J is named in the same sentence as 2 diseases in open-access papers, as found by Europe PMC text mining. Sharing a sentence is not in itself a finding about the gene and the disease. The quoted sentences say what the papers report.
colorectal cancer (1 paper, 2023). A primary or metastatic malignant neoplasm that affects the colon or rectum. "Our RNA-Seq analysis also found that 5’-Aza-CdR exposure resulted in overexpression of multiple CT antigens in gastric cancer and colorectal cancer, including SSX1, TKTL1, SPANXB1, PNMA5, PNMA6E, GAGE12J, and PRSS56." (PMID 37400936, 2023).
GAGE12J also shares sentences with these, for which no sentence is quoted: gastric cancer (1 paper).